ZBTB4 (zinc finger and BTB domain containing 4)
Diseases named in the same sentence as ZBTB4 in open-access papers (continued):
Sharing a sentence is not in itself a finding about the gene and the disease.
cancer (continued). "Also it was part of a miR-17-92-ZBTB4-Sp transcription factor network that determined the inversely correlated expression of ZBTB4 and Sp1, which were positive and negative prognostic factors, respectively, for survival/relapse-free survival of cancer patients." (PMID 28978185, 2017). "In our study, ZBTB4 was remarkably correlated with TMB and MSI in pan-cancer, and we can speculate that ZBTB4 is a powerful biomarker for predicting response to cancer immune checkpoint inhibitor blockade therapy." (PMID 36949454, 2023). "Previous studies have identified aberrant ZBTB4 expression in cancer and its ability to modulate disease progression, but studies on the immune microenvironment, immunotherapy and its role in cancer are still lacking." (PMID 36949454, 2023). "Transfection of MCF-7 and MDA-MB-231 cancer cells with miRNA-20a, miRNA-106a and miRNA-106b antagomirs led to evident suppression in the levels of Sp1, Sp3, Sp4 and EZH2, but, simultaneously, there was an increase in the levels of ZBTB4." (PMID 36615262, 2022). "ZBTB4 is frequently downregulated in cancer, and a mouse model shows that a lack of ZBTB4 increases genome instability." (PMID 35625988, 2022).
tumor (18 papers, 2015 to 2025). "In summary, ZBTB4 is associated with alteration of the tumor immune microenvironment, immunotherapy efficacy and tumor prognosis." (PMID 36949454, 2023). "In addition, we explored the relationship between ZBTB4 expression and tumor immune cell infiltration, tumor mutational burden (TMB), microsatellite instability (MSI) and multiple molecular signal pathways." (PMID 36949454, 2023). "Loss of the ZBTB4 gene, a transcriptional repressor gene that binds to the GC-rich promoter regions of their targets, increases genomic instability (aneuploidy) and promotes tumorigenesis in human neoplasia, including PC." (PMID 30925701, 2019). "ZBTB4 was closely related to the tumor immune microenvironment, immune cell infiltration and immunotherapy efficacy." (PMID 36949454, 2023). "The results showed that ZBTB4 expression was significantly lower in many tumor tissues than in the corresponding healthy tissues." (PMID 36949454, 2023). "We confirmed global epigenetic modification associated with reduced H4R3me2S and re-expression of tumour suppressors, such as EIF3F, FOXP4, ZBTB4, GANAB, TMEM141, in association with loss of clonogenicity." (PMID 33795785, 2021). "To confirm the roles of MSI2, SNORD12B, and ZBTB4 in tumor growth in vivo, we subcutaneously injected GBM MSI2(−) cells, SNORD12B(−) cells, ZBTB4(+) cells, or a combination of the three cells to construct mouse xenograft models." (PMID 34047477, 2021). "The miR-17-92 cluster members can also suppress the specificity protein (Sp) repressor ZBTB4, which in turn facilitates upregulation of Sp transcription factors and their target genes, thereby displaying tumor promoting functions." (PMID 31581940, 2019). "In conclusion, our findings demonstrate that ZBTB4 can modulate the tumor microenvironment." (PMID 36949454, 2023). "It was significantly correlated with many immune cell infiltrations in most tumors, suggesting that ZBTB4 may influence disease progression and prognosis through the tumor immune microenvironment." (PMID 36949454, 2023). "As a tumor suppressor, ZBTB4 can affect the tumor immune microenvironment, and may be a potential tumor immunotherapy target." (PMID 36949454, 2023). "Recent studies found that ZBTB4 mainly acts as a transcription inhibitor in tumor cells." (PMID 34047477, 2021). "For instance, increased ZBTB4 expression in tumours is a prognostic factor for increased survival." (PMID 32365491, 2020). "Decreased levels of ZBTB4 in the tumor correlated with higher genomic instability." (PMID 31245293, 2019). "Among the underexpressed genes, we observed the DNAm reader ZBTB4, whose expression has been significantly correlated with relapse-free survival, as well as the polycomb component and K36 reader, CBX7, which has already been implicated as a tumor suppressor." (PMID 26169266, 2015). "Therefore, we speculated that M2 macrophage-derived exosomes reduce the expression of ZBTB4, thereby promoting the formation of a tumor-friendly microenvironment and facilitating tumor metastasis in advance." (PMID 38655063, 2024). "Similarly, ZBTB4 functions as a tumor suppressor in various tumors." (PMID 34047477, 2021). "Moreover, ZBTB4 restoration would suppress the tumor growth in mice." (PMID 31480180, 2020). "TRIM69, Ube2j1, ZBTB4, and SKP2 show the most pronounced effects on the immune microenvironment of the tumor." (PMID 40697329, 2025). "Previous studies indicated that ZBTB4 and PDGFRA played roles in tumor progression, same as our prediction." (PMID 34484284, 2021). "The results showed that NEBL, PDGFRA and ZBTB4 were upregulated in OC tissues compared to in normal ovarian tissues, whereas WDR91 were downregulated in tumor tissues." (PMID 34484284, 2021). "It exercises its role as a tumor suppressor by negatively regulating the expression of target genes such as PTEN, TGFBR2, ZBTB4 and SMAD4." (PMID 31200745, 2019).
tumor (continued). "Moreover, the differential expression of TRIM69, Ube2j1, ZBTB4, and SKP2 likely serves a critical function in modulating tumor immune infiltration." (PMID 40697329, 2025). "Overexpression of tumour suppressors, such as EIF3F, FOXP4, ZBTB4, GANAB, TMEM141 was observed." (PMID 33795785, 2021). "It would thus be interesting to investigate whether a combination between expression levels of ZBTB4, ZBTB33/KAISO and ZBTB38 may help better categorised tumours with different molecular and clinical behaviour." (PMID 32365491, 2020). "These miRNAs promote tumour progression via: reduced stiffness of the extracellular matrix due to reduced expression of PTEN (mir-18a), facilitation of cell migration and metastasis (mir-18b), suppression of tumour suppressor genes ZBTB4 and Rb(mir-106b)." (PMID 26152113, 2015).
intestinal disease (1 paper, 2022). "Furthermore, the possibility of a redundant function between Kaiso and ZBTB4 warrants further investigation to fully understand the role of Kaiso in faulty cell adhesion, Wnt signaling, and intestinal disease." (PMID 36274850, 2022). "As there have been few studies examining the function of ZBTB4 in the mammalian intestine or canonical Wnt signaling, further studies are needed to determine if ZBTB4 does in fact function somewhat redundantly in the absence of Kaiso and its potential roles in intestinal diseases." (PMID 36274850, 2022).
ZBTB4 also shares sentences with these, for which no sentence is quoted: adenocarcinoma (1 paper); age (1); Anophthalmia (1); coloboma (1); connective tissue disorder (1); endometrial cancer (1); glioblastoma (1); infection (1); lung adenocarcinoma (1); microcephaly (1); microphthalmia (1); pancreatic adenocarcinoma (1); retinoblastoma (1).